BRAF (B-Raf proto-oncogene, serine/threonine kinase)
Diseases named in the same sentence as BRAF in open-access papers (continued):
Sharing a sentence is not in itself a finding about the gene and the disease.
cutaneous melanoma (569 papers, 2003 to 2026). A primary melanoma arising from atypical melanocytes in the skin. "Conversely, in CoM, the mutational spectrum overlaps with cutaneous melanoma, with frequent alterations in BRAF, NRAS, NF1, and KIT, offering actionable targets for personalised treatment." (PMID 41751395, 2026). "BRAF mutations frequency has little difference among races, BRAF mutations in cutaneous melanoma account for approximately 50% in Caucasians and Asians, and BRAF mutations in acral melanoma account for about 15% in Caucasians and Asians." (PMID 41492362, 2026). "Demographic and clinical features of 40 patients with stage III or IV cutaneous melanoma harboring BRAF mutation." (PMID 40994966, 2025). "With the addition of targeted therapies directed against activating BRAF mutations (found in ∼40% of cutaneous melanomas), over half of patients today with advanced cutaneous melanoma will survive for more than 5 years after their initial diagnosis." (PMID 41325134, 2025). "In cutaneous melanoma, improved understanding of the high frequency of BRAF mutations has led to the development of targeted therapies with BRAF and MEK inhibitors." (PMID 41295253, 2025). "Around 50% of primary cutaneous melanomas show BRAF mutations, and out of these, 90% are a distinct mutant variant that forms by the replacement of valine by glutamic acid on exon 15 of the BRAF gene, named the BRAF V600E mutant variant." (PMID 40507250, 2025). "GNAQ and GNA11 mutations are prevalent in primary CNS melanoma but differ from cutaneous melanoma (CM), in which BRAF, NRAS, KIT, and NF-1 mutations are more common." (PMID 41536409, 2025). "Genetic mutations in mucosal melanoma are reportedly one-fifth to one-tenth as frequent as in cutaneous melanoma, and BRAF mutations are particularly rare in mucosal subtypes." (PMID 41487751, 2025). "Half of cutaneous melanoma cases involve BRAF mutations, which drive cancer growth via mitogen-activated protein kinase (MAPK) pathway activation." (PMID 41170188, 2025). "An important consideration is the prevalence of BRAF mutations (particularly V600E) in cutaneous melanoma and its potential interplay with the KRAS-associated pathways investigated here." (PMID 40607411, 2025). "Cutaneous melanoma is a malignant and metastatic tumour with an oncogenic mutation V600E in B‐Raf proto‐oncogene serine/threonine kinase (BRAF)." (PMID 40817681, 2025). "In cutaneous melanoma, most commonly driven by BRAF or NRAS mutations, ICIs have demonstrated substantial improvements in overall survival and durable clinical responses." (PMID 41301010, 2025). "In cutaneous melanoma, activating BRAF mutations (predominantly V600E/K) are commonly reported in approximately 40-56% of contemporary series, and NRAS mutations occur in 15- 30%." (PMID 41384184, 2025). "Most cutaneous melanomas harbor activating mutations in BRAF or NRAS, but a distinct subset is defined by the oncogenic activation of KIT through somatic mutations." (PMID 41301010, 2025). "The reported frequencies of mutations in cutaneous melanoma are 37–60% in BRAF, 13–25% in NRAS, 12% in NF1, 6–7% in MAP2K1, and 2–8% in KIT." (PMID 41295253, 2025). "In contrast, BRAF mutations are the most common for cutaneous melanomas, making up approximately 50–60%." (PMID 40447784, 2025). "The MAPK/ERK pathway regulator BRAF was included, as mutations in the V600E variant are present in approximately 50–60% of human cutaneous melanomas." (PMID 40647405, 2025). "In this context, The Cancer Genome Atlas (TCGA) project classifies cutaneous melanoma into four major genomic subtypes based on driver mutations: BRAF-mutant, RAS-mutant, NF1-mutant, and triple wild-type." (PMID 41465101, 2025).
cutaneous melanoma (continued). "As expected, the majority of patients had cutaneous melanoma and approximately 30% of patients harboured a BRAF mutation." (PMID 40805161, 2025). "It is important to acknowledge that direct activating mutations in KRAS are relatively infrequent in cutaneous melanoma (<5% in TCGA) compared to BRAF or NRAS mutations." (PMID 40607411, 2025). "The majority of patients (82%) had a cutaneous melanoma primary site, and 44% of the patients presented BRAF V600 mutations." (PMID 39796770, 2025). "Whilst targeted therapies directed against activating BRAF mutations (found in ∼40% of cutaneous melanomas) have played a role, it is modern immunotherapies which have delivered the bulk of long-term survival gains." (PMID 41325134, 2025). "ARM are clearly distinguished from cutaneous melanomas by a lower frequency of BRAF mutations and a higher prevalence of c-KIT gene alterations, observed in around 35.5% of cases." (PMID 40978962, 2025). "Vemurafenib, a low‐molecular‐weight BRAF inhibitor, effectively treats cutaneous melanoma with the BRAFV600E mutation, but it causes skin disorders such as dry skin with high frequency." (PMID 40817681, 2025). "Given the high frequency of BRAF mutation in cutaneous melanoma, greater clarity on the effect of BRAF mutation on adjuvant anti‐PD1 monotherapy will be of clinical utility." (PMID 41342263, 2025). "Targeted therapies, including BRAF inhibitors (e.g., vemurafenib and dabrafenib) and MEK inhibitors (e.g., trametinib), have shown significant efficacy in BRAF-mutated cutaneous melanomas." (PMID 40003600, 2025). "In this study cutaneous melanomas were evaluated to identify the correlation between clinical, histopathological, dermoscopic features, and BRAF, NRAS, and cell cycle genes’ mutational status." (PMID 40867317, 2025). "Primary cutaneous melanomas that harbourthe mutation can respond to inhibitor treatments, like BRAF inhibitors, which include vemurafenib, dabrafenib, and encorafenib, and MEK inhibitors, like trametinib, binimetinib, and cobimetinib." (PMID 40507250, 2025). "Although BRAF is the most frequently mutational oncogene in cutaneous melanoma, studies of sinonasal melanomas show a higher prevalence of NRAS mutations compared to BRAF mutations." (PMID 41369373, 2025). "For cutaneous melanoma, head/neck tumours had the lowest odds of being BRAF mutated (OR 0.43, 95% CI 0.38–0.48)." (PMID 40902091, 2025). "The alternative to ICI is targeted therapy aimed at driver mutations, with BRAF being the most prevalent mutation in cutaneous melanoma and c-KIT being the most prevalent mutation in mucosal melanoma." (PMID 39207855, 2024). "The V600E mutations of BRAF, namely the substitution of valine with glutamic acid at codon 600, were detected in over 90% of acquired melanocytic nevi and over 50% of cutaneous melanomas." (PMID 39273022, 2024). "Over 50% of cutaneous melanomas harbor BRAF mutations, which can induce an enhancement of the kinase action that, consequently, leads to activation and augmentation of the downstream MAPK signaling pathway." (PMID 38541077, 2024). "Point mutations at codon 600 of the BRAF oncogene are the most common alterations in cutaneous melanoma (CM)." (PMID 39735251, 2024). "The well-known mutated genes involved in cutaneous melanoma have only a marginal role in MM, and the infrequent rate of BRAF V600E mutation observed in MM limits the efficacy of BRAF inhibitors." (PMID 38315310, 2024). "The MAPK pathway plays a central role, with BRAF mutations occurring in approximately 50% of cutaneous melanomas, most commonly the BRAFV600E alteration." (PMID 39518150, 2024). "First, we examined a clinical study of 39 cutaneous melanoma patients treated with either dabrafenib or vemurafenib, another targeted inhibitor of oncogenic BRAF V600X mutations (Section 2)." (PMID 38940147, 2024).
cutaneous melanoma (continued). "Further, we sought to explore potential correlations between BRAF mutational status and the clinicopathological features of the tumors to obtain a more comprehensive understanding of the role of this mutation in cutaneous melanoma." (PMID 38396984, 2024). "The Cancer Genome Atlas (TCGA) project has identified distinct subtypes of cutaneous melanoma (CM), primarily defined by mutations in BRAF, RAS, NF1, and triple wild‐type subtypes." (PMID 39564955, 2024). "Typical mutations present in cutaneous melanoma (CM) are BRAF (v-raf murine sarcoma viral oncogene homolog B1) V600E (found in approximately 50% of the cases), but BRAF mutations are found in only 10-35% of AM and 0-21% of MM." (PMID 38469235, 2024). "Mutations that are noted in mucosal melanoma include neurofibromin 1 (NF1), KIT, and splicing factor 3b subunit 1 (SF3B1); NRAS and BRAF mutations occur at far lower rates than traditional cutaneous melanoma." (PMID 39001457, 2024). "Targeted therapy has shown excellent results in metastasized cutaneous melanoma as BRAF-mutations are present in more than half of all patients." (PMID 38761218, 2024). "BRAF is a serine/threonine-specific protein kinase that is mutated in 50∼70% of cutaneous melanomas." (PMID 38519031, 2024). "Somatic mutations in BRAF have been found in 60–70% of cutaneous melanomas but in only a few cases of PMME." (PMID 37861097, 2024). "A375 is a skin melanoma cell line with the BRAF-V600E mutation, while MeWo cells harbor wild-type BRAF." (PMID 38243170, 2024). "Here, we review the main mutations associated with cutaneous melanoma, focusing on the BRAF, MEK, and KIT genes." (PMID 39202970, 2024). "Studies have shown that cutaneous melanomas are often linked to the BRAF V600E mutation, whereas AMMs are more frequently associated with a c-KIT mutation." (PMID 39449907, 2024). "In line with this understanding, our results suggested that RC48, either alone or in combination with dabrafenib, has the potential to improve treatment outcomes for HER2-low patients with BRAF-mutated cutaneous melanoma." (PMID 38594618, 2024). "About 50% of cutaneous melanoma (CM) patients present activating BRAF mutations that can be effectively targeted by BRAF inhibitors (BRAFi)." (PMID 38510242, 2024). "Much progress has been made in the past 10–15 years with targeted therapies against mutated BRAF, the most common mutation in cutaneous melanoma, and immune-checkpoint blockade immunotherapies." (PMID 38732030, 2024). "While the pathogenesis of MM has not been fully elucidated, certain mutational profiles seem to be characteristic—c-KIT tends to be found in increased frequency in MM whereas BRAF mutations are rare; the converse is true in cutaneous melanomas." (PMID 39416390, 2024). "SF3B1 and KIT have been shown to have a higher mutation rate in MM as compared to cutaneous melanoma, whereas BRAF and NRAS have a lower mutation rate in MM." (PMID 39416390, 2024). "Targetable mutations commonly seen in cutaneous melanoma, such as in the BRAF and NRAS genes, have a lower incidence in mucosal melanoma." (PMID 38778387, 2024). "For example, BRAF mutant cutaneous melanoma is the most common subtype, with the V600E mutation occurring in most patients." (PMID 38254853, 2024). "In humans, BRAF mutation plays an important role in the pathogenesis of UV-exposed cutaneous melanoma; there is a low frequency of BRAF mutations in dogs, consistent with their differing etiologies [LOE 2b, OEG B]." (PMID 38645640, 2024). "Reported rates of BRAF mutation in Irish cutaneous melanoma cohorts are lower than the reported international data." (PMID 38183457, 2024). "In terms of targeted therapies, roughly 40-60% of cutaneous melanoma possess a BRAF V600 mutation, which can be effectively treated with inhibitors of BRAF and the downstream target MEK." (PMID 38500654, 2024).
cutaneous melanoma (continued). "In cutaneous melanomas, the most common subtype, a high mutational burden, particularly in the BRAF gene, has led to the development of BRAF inhibitors (BRAFi) such as vemurafenib and dabrafenib." (PMID 39199633, 2024). "Half of all cutaneous melanomas harbour activating BRAF mutations, of which 80% of them are BRAF V600E." (PMID 39661469, 2024). "For example, genome sequencing has revealed that ∼50% of all cutaneous melanomas harbor a mutation in the BRAF gene." (PMID 38213996, 2024). "This study involved only Italian centers and described the use of dabrafenib and trametinib in an Italian real-world practice to treat patients with either limited or bulky BRAF V600E/K or other BRAF-activating mutation-positive cutaneous melanoma." (PMID 37046641, 2023). "The choice of adjuvant treatment for individuals with surgically excised cutaneous melanoma depends on multiple determinants, including tumor stage, BRAF mutation status, the probability of relapse, comorbid conditions and patient wishes." (PMID 37627153, 2023). "The mutational landscape of non-BRAF skin melanoma, in light of recent data deriving from WES or WGS studies, includes 33 candidate driver genes altered with a frequency greater than 1.5%." (PMID 36901733, 2023). "In the majority of the most common histological forms, cutaneous malignant melanoma is a genetically well-defined tumor with clear driver and suppressor profiles dominated by BRAF and CDKN2A mutations." (PMID 36980598, 2023). "At the same time, therapies (BRAF plus MEK inhibitors) targeting the BRAFV600 mutations found in 40–50% of cutaneous melanomas have also been critical for optimizing management and improving patient outcomes." (PMID 37370834, 2023). "The majority of BRAF mutations in cutaneous melanoma are missense, resulting in amino acid substitutions at the valine 600 position." (PMID 37958863, 2023). "NRAS is the second most common driver mutation in cutaneous melanoma, second only to BRAF, and is found in 25–30% of cases." (PMID 37370834, 2023). "Acral melanomas share many similar driver mutations with cutaneous melanomas, with BRAF (10–34.4%) being the most frequently mutated gene in both Asian and Caucasian cohorts." (PMID 37239381, 2023). "Cutaneous melanoma remains the deadliest form of skin cancer, with a rapidly increasing global incidence, and 30–50% of patients carry oncogenic BRAF mutations, such as the common V600E substitution." (PMID 37189846, 2023). "It is now well-established that UM and primary orbital melanoma result from driver mutations in the GNAQ and GNA11 genes, whereas cutaneous melanoma and CM result from mutations in the BRAF, NRAS, NF1, and c-Kit genes." (PMID 37190299, 2023). "The mutational drivers of cutaneous melanoma change with age - BRAF is the most common driver in the young, while NRAS and other mutations increase in prevalence with increasing age." (PMID 36909026, 2023). "The rate of NF1 mutations is comparable to that of cutaneous melanoma (~14%); however, BRAF/NRAS mutations rates are remarkably lower, and KIT mutations are observed in at least 13% of cases." (PMID 38201222, 2023). "Mutations in BRAF, particularly the V600E, are frequently harbored in patients with cutaneous melanoma." (PMID 37895015, 2023). "Patients with completely resected stage-III cutaneous melanoma harboring BRAF V600E or V600K mutations showed improved RFS and OS when they received dabrafenib-plus-trametinib as an adjuvant treatment." (PMID 38139110, 2023). "Currently, the targeted therapy of BRAF has become the first-line treatment scheme for skin melanoma with advanced BRAF mutation." (PMID 36891324, 2023).
cutaneous melanoma (continued). "In this context, an advanced DDI detection software (Drug-PIN, V. 2/23) was used to assess the DDIs in a retrospective cohort of 177 patients with metastatic BRAF-mutated cutaneous melanoma treated with BRAF and MEK inhibitors." (PMID 37760556, 2023). "This panel included cell lines representing all four molecular subtypes of cutaneous melanoma with driver mutations in the BRAF, NRAS, or NF1 genes and a fourth triple wild-type subtype, in which none of these genes are mutated." (PMID 37803324, 2023). "BRAF mutations are present in 30–50% of cases of cutaneous melanoma, and treatment with selective BRAF and MEK inhibitors has been introduced." (PMID 37189846, 2023). "Results from this study will likely bolster ctDNA even more as a dynamic biomarker that can be incorporated into daily clinical practice of BRAF-mutated cutaneous melanoma." (PMID 38201222, 2023). "Patient 4 was a 51-year-old man, diagnosed with stage-IV cutaneous melanoma harboring a BRAF-V600E mutation." (PMID 35841421, 2023). "BRAF mutations are extremely common in cutaneous melanoma, with approximately 40% of patients harboring a BRAF mutation, most commonly the V600E genotype." (PMID 36276131, 2022). "BRAFV600E mutations are typically found in cutaneous melanoma areas without sun damage and develop from nevi, while atypical mutations in BRAF are found in sun exposed skin melanoma." (PMID 35163401, 2022). "Skin cutaneous melanoma is one of the deadly diseases, and more than 50% of the patients have BRAF gene mutations." (PMID 36531226, 2022). "Driver mutations in choroidal melanomas are mutations in the heterotrimeric G-protein alpha subunits GNAQ and GNA11, while conjunctival melanomas show more resemblance to skin melanoma with oncogenic mutations in BRAF and NRAS." (PMID 35682684, 2022). "Around 40–50% of patients with cutaneous melanoma harbor such mutations located in codon 600 of the BRAF gene." (PMID 35159044, 2022). "Uveal melanoma has radically different genetic causes compared to cutaneous melanoma because mutations in BRAF or NRAS are exceedingly rare." (PMID 35234863, 2022). "Targeted inhibition of oncogenic BRAFV600 along with MEK, which is directly downstream of BRAF, is a mainstay of treatment for cutaneous melanoma with mutated BRAF." (PMID 36271142, 2022). "The frequency of BRAF mutations in AM is much lower than that in cutaneous melanoma, which prevents most AM patients from receiving treatment with BRAF inhibitors." (PMID 36125617, 2022). "While BRAF mutation occurs up to 50% in cutaneous melanoma, its incidence has been reported to be 4–12% in mucosal melanoma." (PMID 35351022, 2022). "B‐Raf V600E mutations account for about half of all skin cutaneous melanoma cases, and patients with this mutation are sensitive to BRAF inhibitors." (PMID 35044091, 2022). "Compared with cutaneous melanoma, BRAF mutations were less observed in acral melanoma, while mutant NRAS (26.7%) and Triple-WT (7/15, 46.7%) were more common." (PMID 35688842, 2022). "Approximately 50% of cutaneous melanoma cases carry BRAF mutations of which over 90% are BRAF V600E mutations." (PMID 36077308, 2022). "The association of dabrafenib (150 mg twice daily) and trametinib (2 mg once daily) in unresectable or metastatic BRAF V600E- or V600K-mutated cutaneous melanoma was evaluated in two randomized controlled trials (COMBI-d study and COMBI-v study)." (PMID 35742834, 2022). "In our study, mutant BRAF (51.1%,23/45) of cutaneous melanoma in Chinese was similar to that in Caucasians, and BRAF V600E/K was the commonest mutation." (PMID 35688842, 2022).